ATP2B4 (ATPase plasma membrane Ca2+ transporting 4)
Description:
Calcium/calmodulin-regulated and magnesium-dependent enzyme that catalyzes the hydrolysis of ATP coupled with the transport of calcium out of the cell. By regulating sperm cell calcium homeostasis, may play a role in sperm motility (By similarity).
Synonyms: PMCA4; ATP2B2; MXRA1; PMCA4b; PMCA4x
Tractability: Small molecule: it belongs to a druggable protein family. Antibody: UniProt places it where antibodies can reach, with high confidence; its Gene Ontology location is reachable by antibodies, with high confidence; UniProt predicts a signal peptide or a membrane-spanning region; the Human Protein Atlas places it where antibodies can reach. PROTAC: ubiquitination databases record sites on it; its protein half-life has been measured.
Gene: Protein-coding gene on chromosome 1 (203,626,778 to 203,744,081, forward strand). Ensembl gene ENSG00000058668.
Subcellular location: Cell membrane; Cell projection, cilium, flagellum membrane
Subcellular location (Human Protein Atlas): Plasma membrane; Primary cilium; Basal body; Mitochondria
Pathways (Reactome):
Hemostasis: Reduction of cytosolic Ca++ levels
Muscle contraction: Ion homeostasis
Transport of small molecules: Ion transport by P-type ATPases
Gene Ontology:
Molecular function: calcium ion transmembrane transporter activity; calmodulin binding; nitric-oxide synthase binding; nitric-oxide synthase inhibitor activity; P-type calcium transporter activity; protein binding; protein phosphatase 2B binding; scaffold protein binding; sodium channel regulator activity; ATP binding; ATP hydrolysis activity; nucleotide binding; PDZ domain binding; protein kinase binding
Biological process: calcium ion export; calcium ion transmembrane transport; cellular response to epinephrine stimulus; intracellular calcium ion homeostasis; negative regulation of adenylate cyclase-activating adrenergic receptor signaling pathway; negative regulation of angiogenesis; negative regulation of arginine catabolic process; negative regulation of blood vessel endothelial cell migration; negative regulation of calcineurin-NFAT signaling cascade; negative regulation of cardiac muscle hypertrophy in response to stress; negative regulation of cellular response to vascular endothelial growth factor stimulus; negative regulation of citrulline biosynthetic process; negative regulation of gene expression; negative regulation of nitric oxide biosynthetic process; negative regulation of the force of heart contraction; nitric oxide-cGMP-mediated signaling; positive regulation of protein localization to plasma membrane; regulation of cell cycle G1/S phase transition; regulation of transcription by RNA polymerase II; response to hydrostatic pressure; calcium ion import across plasma membrane; calcium ion transmembrane import into cytosol; cellular response to acetylcholine; flagellated sperm motility; monoatomic ion transmembrane transport; and 9 more
Cellular component: membrane; membrane raft; plasma membrane; T-tubule; Z disc; caveola; protein-containing complex; sperm flagellum; basolateral plasma membrane; glutamatergic synapse; presynaptic active zone membrane; sarcolemma; sperm principal piece
Genetic constraint (gnomAD): Loss-of-function variants: 38 observed, 113.21 expected, observed/expected ratio (o/e) 0.34, 90% interval 0.26 to 0.44. The upper end of that interval is the gene's LOEUF score, 0.44, which puts it in group 1 of 6, group 1 being the genes least tolerant of losing a copy. Missense variants: 1,091 observed, 1,554.4 expected, observed/expected ratio (o/e) 0.7, 90% interval 0.67 to 0.74. Synonymous variants: 520 observed, 583.07 expected, observed/expected ratio (o/e) 0.89, 90% interval 0.83 to 0.96.
Homologues: Orthologues: chimpanzee ATP2B4 (99% identical), macaque ATP2B4 (98% identical), dog ATP2B4 (91% identical), guinea pig ATP2B4 (90% identical), rat Atp2b4 (85% identical), mouse Atp2b4 (85% identical), pig ATP2B4 (84% identical), tropical clawed frog atp2b4 (80% identical), zebrafish atp2b4 (77% identical), Drosophila melanogaster PMCA (61% identical), Caenorhabditis elegans catp-2 (19% identical), Caenorhabditis elegans catp-3 (18% identical), and 1 more. Paralogues in human: ATP2B1 (77% identical), ATP2B3 (76% identical), ATP2B2 (75% identical), ATP2A2 (25% identical), ATP1A1 (24% identical), ATP2A1 (24% identical), ATP1A2 (24% identical), ATP2A3 (24% identical), ATP1A3 (24% identical), ATP1A4 (23% identical), ATP12A (23% identical), ATP2C1 (23% identical), and 9 more.
Diseases named in the same sentence as ATP2B4 in open-access papers:
ATP2B4 is named in the same sentence as 80 diseases in open-access papers, as found by Europe PMC text mining. Sharing a sentence is not in itself a finding about the gene and the disease. The quoted sentences say what the papers report.
malaria (36 papers, 2013 to 2026). Malaria is a serious and sometimes fatal disease caused by a parasite that commonly infects a certain type of mosquito which feeds on humans. "At the genetic level, multiple single-nucleotide polymorphisms (SNPs) in the regulatory regions of ATP2B4 confer protection against severe and mild malaria." (PMID 41400477, 2026). "This study evaluates ATP2B4 genotypes and PMCA4b expression in malaria susceptibility and artemisinin sensitivity." (PMID 41400477, 2026). "The protective ATP2B4 genotype is prevalent in populations from The Gambia and other malaria-endemic regions, and is associated with significantly reduced peripheral parasitemia during infection." (PMID 40993672, 2025). "The current challenge is to link the ATP2B4 Epromoter to the genes and specific cell types it affects to uncover the mechanisms driving malaria susceptibility." (PMID 40441141, 2025). "H3K27Ac profiles from Roadmap data, revealed active regulatory elements at the ATP2B4 Epromoter, containing malaria-associated SNPs and the LAX1 promoter in CD4+ T cells." (PMID 40441141, 2025). "Specifically, the rs10900585 variant confers a 64% reduction in the risk of placental P.f infection among homozygous primigravidae, highlighting the potential relevance of ATP2B4 variation in pregnancy-associated malaria." (PMID 40993672, 2025). "Using a recall-by-genotype design, we investigated the impact of a common haplotype variant in ATP2B4 using in vitro assays that model erythrocyte stage malaria pathogenesis." (PMID 36604655, 2023). "Taken together, these data are consistent with the conclusion that polymorphisms in ATP2B4 common in African populations and inherited as a large haplotype block, protect against severe malaria by controlling parasite density." (PMID 36604655, 2023). "The observations on the relationship between several polymorphisms in ATP2B4 and risk of malaria was first demonstrated in Ghanaian and Gambian populations and was subsequently replicated in other African, Asian and Oceanic populations." (PMID 36604655, 2023). "ATP2B4 polymorphisms are widely distributed in malaria endemic regions and have been reproducibly linked to altered susceptibility to malaria in multiple African populations." (PMID 36604655, 2023). "ATP2B4 polymorphisms that have been associated with severe malaria are also associated with mild malaria." (PMID 36849945, 2023). "ATP2B4 SNPs associated with altered resistance to malaria by GWAS are numerous and found in the region from the first to the third exon spanning a 16.5 kilobase (KB) region." (PMID 36604655, 2023). "Other GWAS and candidate gene studies conducted in Burkina Faso, Cameroon, Gambia, Kenya, Mali, Malawi, or Tanzania confirmed the association of the ATP2B4 gene with severe malaria." (PMID 36849945, 2023). "ATP2B4 minor allele haplotype that protects against severe malaria also protects against mild malaria in a Senegalese population." (PMID 36849945, 2023). "Our data demonstrate that severe malaria-associated genetic variants alter the expression of ATP2B4 encoding a plasma membrane calcium-transporting ATPase 4 (PMCA4) expressed on red blood cells." (PMID 35563239, 2022). "Based on these studies, it has been established that an erythroid-specific regulatory region of the ATP2B4 gene is present in the first intron region, and SNPs located in this region significantly affect both PMCA4b expression and susceptibility to malaria." (PMID 34436349, 2021). "The ATP2B4 gene polymorphism has been suggested to be a malaria-driven selection force in some African regions." (PMID 34436349, 2021). "This overlap is driven by well-known genetic variation in the beta-hemoglobin gene (HBB) and ABO blood type affecting malaria risk but also by genetic variation in ATP2B4 which encodes a calcium transporter." (PMID 34001247, 2021).
malaria (continued). "Recent genome wide analysis studies have identified a strong association between single nucleotide variations within the human ATP2B4 gene and susceptibility to severe malaria." (PMID 34215257, 2021). "The role of ATP2B4 gene polymorphisms, as one of the potentially important factors in malaria susceptibility, has recently attracted much attention and initiated both experimental and computational studies (see references below)." (PMID 34436349, 2021). "In the remaining genomic risk loci, the well-known genes that play role in severe malaria resistance including ATP2B4 (chr1q32), FREM3, GYPE, and GYPB (chr4p31) were replicated and few additional genes were identified." (PMID 34868193, 2021). "We also found strong associations between overall risk of severe malaria and polymorphisms in both ATP2B4 (OR 0·76, 95% CI 0·63–0·92; p=0·001) and FREM3 (0·64, 0·53–0·79; p=3·18 × 10−14)." (PMID 30033078, 2018). "A significant association signal of ATP2B4 was first identified in a genome-wide association case-control study of severe malaria undertaken in Ghana, and replicated in subsequent severe malaria case-control studies." (PMID 30033078, 2018). "The polymorphism rs1541255 in ATP2B4 was common in our study population, with an allele frequency of 33% among controls, consistent with selection through a survival advantage against malaria." (PMID 30033078, 2018). "Further studies are being done to confirm the precise mutation within ATP2B4 that is associated with malaria protection and describing its effects both on tissue-specific PMCA4 structure and function and on malaria-specific pathophysiological processes." (PMID 30033078, 2018). "Further polymorphisms associated with severe malaria were noted for rs1541255 in ATP2B4 (adjusted OR 0·76, 95% CI 0·63–0·92; p=0·001) and rs186873296 located in an intergenic region between FREM3 and GYPE (0·64, 0·53–0·79; p=3·18 × 10−14)." (PMID 30033078, 2018). "Additional work in Ghana has shown protective effects of ATP2B4 on malaria in pregnancy and related maternal anemia, suggesting that ATP2B4 variant-associated protection is not limited to severe childhood malaria." (PMID 25805752, 2015). "Several SNPs of ATP2B4 gene have been studied for their association with malaria protection." (PMID 41400477, 2026). "Additionally, polymorphisms in the human ATP2B4 gene, encoding a calcium channel, are associated with malaria protection." (PMID 41400477, 2026). "The ATP2B4 gene, encoding the PMCA4b Ca2+-ATPase in erythrocytes, has been linked to malaria protection via genome-wide association studies, though the proposed dehydration mechanism remains unclear." (PMID 41400477, 2026). "Interestingly, the ATP2B4 minor haplotype, protecting against malaria, correlated with an increased disease susceptibility, while in diabetic patients disease susceptibility was lower in the presence of a reduced-function ABCG2 transporter variant." (PMID 39752416, 2025). "Single nucleotide polymorphisms in the ATP2B4 gene that encodes PMCA4 have been associated with resistance to severe malaria in several Genome Wide Association Studies leading to widespread interest in the putative contribution of this protein in P. falciparum invasion, growth and pathogenesis." (PMID 38315723, 2024). "Furthermore, mutations in the ATP2B4 gene, encoding PMCA4, were protected against severe forms of malaria." (PMID 39392480, 2024). "Genome-wide association studies have identified ATP2B4 as a severe malaria resistance gene." (PMID 36849945, 2023). "Therefore, the reduction of parasite growth mediated by the variant ATP2B4 haplotype will likely diminish each of these risks and thus explain its association with severe malaria." (PMID 36604655, 2023). "Thus, it is expected that ATP2B4 genetic variation is associated with parasitaemia and mild malaria attack, which is caused by parasitaemia above a clinical threshold." (PMID 36849945, 2023).
malaria (continued). "Recent genome-wide association studies have demonstrated that a common single nucleotide polymorphism (SNP) of the ATP2B4 gene encoding a calcium pump called the plasma membrane calcium ATPase 4 (PMCA4) has a very strong association with resistance against severe malaria." (PMID 35768835, 2022). "The malaria-protective SNPs in ATP2B4 also associate with increased mean corpuscular hemoglobin concentration (MCHC) in the red blood cells, and thus may cause a wider disease-connected phenotype." (PMID 34436349, 2021). "Genome-wide association (GWA) studies have indicated that a given set of single nucleotide polymorphisms (SNPs) in ATP2B4 confers resistance to a severe form of malaria among children, protects against malaria and associated maternal anemia, and modulates cell dehydration." (PMID 34436349, 2021). "Diseases associated with ATP2B4 include X-Linked Cerebellar Ataxia and Malaria." (PMID 34070492, 2021). "The biological relationship between ATP2B4 and malaria resistance is mediated by polymorphisms in ATP2B4 changing PMCA4 structure or expression, which leads to a homeostatic disruption of intra-erythrocytic Ca2+ levels that are critical to the development of the Plasmodium parasite." (PMID 30849090, 2019). "As such, several plausible explanations could account for how mutations in ATP2B4 might be relevant to protection against severe malaria that could potentially be exploited for development of therapeutic agents." (PMID 30033078, 2018). "Similarly, ATP2B4 was strongly protective against all forms of severe malaria but, moreover, was associated with lower parasite densities." (PMID 30033078, 2018). "A recent study identified malaria-associated variants in ATP2B4." (PMID 23717212, 2013). "Polymorphisms in ATP2B4 coding for PMCA4b, the primary regulator of erythrocyte calcium concentration, have been shown by GWAS and cross-sectional studies to protect against severe malaria but the mechanism remains unknown." (PMID 36604655, 2023). "PMCA4b is encoded by ATP2B4 gene, which has emerged as a strong malaria resistance candidate in several GWAS and case-control studies in various parts of the world." (PMID 41400477, 2026). "It identified that the previously reported SNPs in ATP2B4 regulatory region are common in studied Indian population, as well in Indigenome database, but the protection against severe/mild malaria cannot be seen in studied samples." (PMID 41400477, 2026). "These variations present in the ATP2B4 gene decreased the likelihood of SM (severe malaria) by 40% in African children while also reducing the odds of placental P. falciparum malaria in African women by 64%." (PMID 41400477, 2026). "ATP2B4 genotypes were compared across severe malaria, uncomplicated malaria, and healthy controls in Indian population." (PMID 41400477, 2026). "These independent and diverse research findings strongly indicate the significant role of ATP2B4 gene in protection toward infection of malaria parasites to human host and suggest RBC dehydration as the causal mechanism." (PMID 41400477, 2026). "Further, genotyping of 14 SNPs of ATP2B4 gene was performed in severe malaria and mild malaria cases." (PMID 41400477, 2026). "Multiple polymorphisms at the ATP2B4 locus, including rs10900585, rs11240734, rs1541252, rs1541253, rs1541254, rs1541255, rs10751450, rs10751451 and rs10751452, with susceptibility to mild malaria, indicating that genetic variation at this locus may influence a broad range of malaria outcomes." (PMID 40993672, 2025). "For example, variants near ATP2B4, PTPRT, MYLK4, VENTX, UROC1, and ACER3 have been linked to differential susceptibility to severe malaria." (PMID 40993672, 2025). "Population genetic analyses have revealed strong signatures of positive selection at the ATP2B4 locus, particularly at rs10900588, in Northern Ugandan populations, providing compelling evidence of malaria-driven evolutionary pressure." (PMID 40993672, 2025).